SIGIRR (single Ig and TIR domain containing)
Description:
Acts as a negative regulator of the Toll-like and IL-1R receptor signaling pathways. Attenuates the recruitment of receptor-proximal signaling components to the TLR4 receptor, probably through an TIR-TIR domain interaction with TLR4. Through its extracellular domain interferes with the heterodimerization of Il1R1 and IL1RAP.
Synonyms: TIR8; IL-1R8
Tractability: Antibody: its Gene Ontology location is reachable by antibodies, with high confidence; UniProt predicts a signal peptide or a membrane-spanning region. PROTAC: ubiquitination databases record sites on it; its protein half-life has been measured.
Gene: Protein-coding gene on chromosome 11 (405,711 to 417,473, reverse strand). Ensembl gene ENSG00000185187.
Subcellular location: Membrane
Subcellular location (Human Protein Atlas): Cytosol; Nucleoli fibrillar center
Pathways (Reactome):
Immune System: Interleukin-37 signaling; MyD88:MAL(TIRAP) cascade initiated on plasma membrane
Gene Ontology:
Molecular function: protein binding
Biological process: negative regulation of Toll signaling pathway; acute-phase response; cell surface receptor signaling pathway; negative regulation of chemokine production; negative regulation of cytokine-mediated signaling pathway; negative regulation of lipopolysaccharide-mediated signaling pathway; negative regulation of interleukin-1-mediated signaling pathway; negative regulation of signal transduction; signal transduction
Cellular component: membrane; cell surface; plasma membrane
Genetic constraint (gnomAD): Loss-of-function variants: 41 observed, 39.38 expected, observed/expected ratio (o/e) 1.04, 90% interval 0.81 to 1.35. The synonymous counts are far from expectation, so gnomAD's model fits this gene poorly and the ratio says little. Missense variants: 599 observed, 508.3 expected, observed/expected ratio (o/e) 1.18, 90% interval 1.1 to 1.26. Synonymous variants: 298 observed, 230.08 expected, observed/expected ratio (o/e) 1.3, 90% interval 1.18 to 1.43.
Homologues: Orthologues: chimpanzee SIGIRR (89% identical), pig SIGIRR (87% identical), dog SIGIRR (86% identical), rat Sigirr (82% identical), mouse Sigirr (81% identical), guinea pig SIGIRR (80% identical), tropical clawed frog sigirr (50% identical), zebrafish sigirr (46% identical). Paralogues in human: IL18RAP (19% identical), IL18R1 (19% identical), IL1RL2 (18% identical), IL1R1 (18% identical), IL1RL1 (17% identical), IL1RAPL1 (16% identical), IL1RAPL2 (15% identical), IL1RAP (13% identical), LAG3 (12% identical), IL1R2 (7% identical).
Diseases named in the same sentence as SIGIRR in open-access papers:
SIGIRR is named in the same sentence as 74 diseases in open-access papers, as found by Europe PMC text mining. Sharing a sentence is not in itself a finding about the gene and the disease. The quoted sentences say what the papers report.
colitis (9 papers, 2008 to 2022). Inflammation of the colon. "For instance, ulcerative colitis in human and colitis in mouse were associated with reduced TIR8/SIGIRR expression by epithelial cells." (PMID 23112799, 2012). "In dextran sulfate sodium-induced colitis model, for example, SIGIRR deficiency leads to much more severe intestinal inflammation in terms of weight loss, intestinal bleeding, local tissue damage and mortality." (PMID 22952899, 2012). "Moreover, loss of SIGIRR in this compartment leads to the exaggerated colitis suffered by C. rodentium infected Sigirr −/− mice." (PMID 23950714, 2013). "For instance, IL-1R signaling was shown to drive intestinal inflammation in DSS-induced colitis, as mice deficient in the single immunoglobulin IL-1 receptor-related IL-1 pathway inhibitory molecule (SIGIRR, also known as TIR8) were more susceptible to DSS-induced colitis compared to controls." (PMID 33562334, 2021). "In agreement withthese findings, the absence of SIGIRR/TIR8, a negative regulator of NF-κB, aggravates colitis-associated carcinogenesis." (PMID 18615187, 2008). "SIGIRR is a negative regulator of TLR and IL-1R signaling, but the identity of the (unregulated) receptor(s) that drive the exaggerated colitis and IEC proliferative responses in infected Sigirr −/− mice is unclear." (PMID 23950714, 2013).
systemic lupus erythematosus (6 papers, 2012 to 2025). An autoimmune multi-organ disease typically associated with vasculopathy and autoantibody production. "Our previous study has demonstrated that SIGIRR gene rs7396562 was associated with the risk of systemic lupus erythematosus (SLE) in a Chinese population." (PMID 34036103, 2021). "Researchers evaluated the functional role of SIGIRR in the pathogenesis of systemic lupus erythematosus (SLE), and the absence of SIGIRR is associated with increased activation of DCs and increased expression of various proinflammatory and antiapoptotic mediators." (PMID 40583347, 2025). "Notably, lack of SIGIRR in C57BL/6lpr/lpr background causes massive lymphoproliferation, production of autoantibodies against numerous lupus autoantigens and autoimmue tissue injury, possibly due to enhanced responses of DCs and B cells to immune complexes containing RNA and DNA antigens." (PMID 22952899, 2012).
autoimmune disease (5 papers, 2012 to 2024). A disorder resulting from loss of function or tissue destruction of an organ or multiple organs, arising from humoral or cellular immune responses of the individual to their own tissue constituents. "The single immunoglobulin and IL-1 receptor (SIGIRR), found up-regulated in our patients 1.55 fold, is implicated in infectious and sterile inflammation, as well as autoimmune disease." (PMID 25889530, 2015). "Additionally, SIGIRR is essential in regulating inflammatory responses induced by infectious diseases, tumors, and autoimmune diseases." (PMID 39461030, 2024).
tuberculosis (5 papers, 2012 to 2022). A chronic, recurrent infection caused by the bacterium Mycobacterium tuberculosis. "It is interesting to note that frequent polymorphisms in the region comprising PKP3, SIGIRR and another gene, TMEM16J, have been linked to susceptibility to tuberculosis, another inflammatory lung disease." (PMID 34415821, 2022). "The ANO9 gene, also known as TMEM16J (anoctamin 9), together with the SIGIRR and the PKP3 genes constitute a polymorphic complex associated with susceptibility to tuberculosis." (PMID 31480266, 2019). "Results obtained with IL-1-blocking antibodies and IL-1RI-deficient mice indicated that in some of these infectious conditions (tuberculosis and P. aeruginosa lung infection), TIR8/SIGIRR played a major role in dampening inflammation induced by IL-1R activation." (PMID 23847621, 2013). "Gene-targeted studies demonstrate that SIGIRR acts as a nonredundant negative regulator in dampening IL-1R and TLR-induced inflammation and tissue damage, including tuberculosis, candidiasis, aspergillosis, Pseudomonas aeruginosa infection and endotoxemia." (PMID 26634342, 2015).
Autoimmunity (4 papers, 2012 to 2025). The occurrence of an immune reaction against the organism's own cells or tissues. "Studies have shown that SIGIRR expression is associated with autoimmunity, inflammatory disorders, graft rejection, viral infection, thrombosis and tumour progression." (PMID 40583347, 2025). "Among them, SIGIRR (also known as TIR8) is of particular interest for its close association with autoimmunity." (PMID 22952899, 2012). "In agreement with the results obtained in autoimmunity mouse models, TIR8/SIGIRR was down modulated together with other anti-inflammatory genes in psoriatic patients." (PMID 23847621, 2013). "Here, we summarize our current understanding of the structure and function of TIR8/SIGIRR, focusing on its role in different pathological conditions, ranging from infectious and sterile inflammation, to autoimmunity and cancer-related inflammation." (PMID 23112799, 2012). "Members of the ILR family have been involved in T cell polarization and proliferation and TIR8/SIGIRR has emerged as a negative regulator affecting Th1, Th2, and Th17 differentiation, which play a major role in autoimmunity and sterile inflammation." (PMID 23112799, 2012).
colorectal cancer (3 papers, 2022 to 2025). A primary or metastatic malignant neoplasm that affects the colon or rectum. "It was reported that loss of N-linked glycosylation on SIGIRR in colorectal cancer blocked the localization of full-length SIGIRR to the surface of colon epithelial cells and its ability to downregulate IL1R signaling." (PMID 36401167, 2022). "In this proteome profiling experiment, we identified a mitochondrial protein, the alpha subunit of adenosine triphosphate (ATP) synthase (ATP5A1), as an interacting protein of SIGIRR in colorectal cancer cells." (PMID 35900274, 2022). "Recently, we have demonstrated that SIGIRR is frequently inactivated in human colorectal cancer by the increased expression of a novel SIGIRR isoform (SIGIRRΔE8)." (PMID 35900274, 2022). "Previously we have shown that tumor suppressor single immunoglobulin interleukin-1-related receptor (SIGIRR) is frequently inactivated in human colorectal cancer by the increased expression of a novel SIGIRR isoform (SIGIRRΔE8)." (PMID 35900274, 2022). "Consistently, SIGIRR localized predominantly to the cytoplasm and colocalized with RPN1 in the colorectal cancer tissues while it is primarily distributed along the basal lateral membrane in normal colonic epithelial cells." (PMID 35900274, 2022).
rheumatoid arthritis (3 papers, 2021 to 2025). A chronic, systemic autoimmune disorder characterized by inflammation in the synovial membranes and articular surfaces. "Additionally, overexpression of SIGIRR also suppresses the spontaneous release of cytokines in human rheumatoid arthritis synovial cells." (PMID 40583347, 2025).
Sepsis (3 papers, 2012 to 2025). Sepsis is defined as life-threatening organ dysfunction caused by a dysregulated host response to infection. "In a mouse model of E. coli pneumonia, 15-epi-LXA4-ALX/FPR2 interaction selectively upregulated the NF-κB negative regulators A20 and SIGIRR, thereby decreasing NF-κB activity, which may inhibit pulmonary neutrophil infiltration while increasing bacterial clearance and improving sepsis survival." (PMID 40799817, 2025). "This, as well as the finding of elevated levels of SIGIRR in monocytes from patients with sepsis or non-infectious systemic inflammatory response, leads to the proposal that SIGIRR provides a feedback regulatory mechanism." (PMID 22952899, 2012).
acute lung injury (2 papers, 2012 to 2020). A condition of lung damage that is characterized by bilateral pulmonary infiltrates (pulmonary edema) rich in neutrophils, and in the absence of clinical heart failure. "In this study, the effects of single immunoglobin IL-1 receptor-related protein (SIGIRR) on tumor necrosis factor- (TNF-) receptor-associated factor 6 (TRAF6) ubiquitination in acute lung injury (ALI) were evaluated in both alveolar epithelial cells and alveolar macrophage cells in vitro." (PMID 33123603, 2020).
acute renal failure (2 papers, 2011 to 2012). "Hence, lack of SIGIRR's inhibitory effect on this signaling pathway aggravates postischemic acute renal failure." (PMID 21544241, 2011).
Arthritis (2 papers, 2022 to 2025). Inflammation of a joint. "An AIA mouse model (antigen-induced arthritis) and CD4 T cells transfer experiments were performed to investigate the effect of SIGIRR deficiency on the development of arthritis in vivo." (PMID 36401167, 2022). "in vivo experiments have revealed the role of SIGIRR as an anti-inflammatory agent, as SIGIRR (−/−) mice exhibited more severe disease in both zymosan-induced arthritis and collagen antibody-induced arthritis models (Ref." (PMID 40583347, 2025). "Mice lacking SIGIRR are more susceptible to antigen-induced arthritis, which is attributed to increased production of TNF-α by memory CD4+ T cells, whereas ectopic expression of SIGIRR leads to decreased production of TNF-α." (PMID 40583347, 2025).
Chronic Lymphocytic Leukemia (2 papers, 2012 to 2022). "In chronic lymphocytic leukemia, SIGIRR is specifically downregulated at both RNA and protein levels." (PMID 35814450, 2022). "In addition to its well-known anti-inflammatory properties, the tumor-suppressive functions of SIGIRR have been recently described in intestinal cancer and chronic lymphocytic leukemia where SIGIRR is specifically downregulated both at mRNA and protein levels." (PMID 35814450, 2022).
fungal infection (2 papers, 2014 to 2017). "We reported that TIR-8/SIGIRR is required for host resistance to fungal infections by reducing IL-1β–dependent activation of inflammatory Th17 responses." (PMID 25375146, 2014). "In fungal infections, signaling through TIR-8/SIGIRR was required for the prevention of lethal inflammatory pathology associated with disregulated IL-1-dependent Th17 responses." (PMID 25375146, 2014).
lupus nephritis (2 papers, 2012 to 2025). Glomerulonephritis in the context of systemic lupus erythematosus. "A specific deficiency in SIGIRR increases the production of rheumatoid factors and anti-snRNP IgG, further exacerbating lupus nephritis in SIGIRR-deficient mice." (PMID 40583347, 2025).
psoriatic arthritis (2 papers, 2012 to 2017). Joint inflammation associated with psoriasis. "In agreement with this study, a gene expression study showed that TIR8/SIGIRR was one among the genes with the most significantly reduced expression in peripheral blood cells of patients with psoriatic arthritis compared to control subjects." (PMID 23112799, 2012).
renal fibrosis (2 papers, 2011 to 2021). A final common manifestation of a wide variety of chronic kidney diseases characterized by glomerulosclerosis and tubulointerstitial fibrosis. "We therefore conclude that SIGIRR is redundant in UUO-induced renal fibrosis because TLR2-, TLR9- and MyD88 signaling do not significantly contribute to this model." (PMID 21544241, 2011).
ulcerative colitis (2 papers, 2012 to 2013). An inflammatory bowel disease involving the mucosal surface of the large intestine and rectum. "TIR8/SIGIRR was therefore a candidate player potentially involved in cancer-related inflammation and was first studied in a model of CAC, a colorectal disease that arises in patients suffering from chronic IBD, in particular Ulcerative Colitis." (PMID 23112799, 2012).
chlamydial infection (1 paper, 2020). "Altogether, our results suggest that SIGIRR is involved in signal transduction via TLRs during chlamydial infection, and down-regulates this signaling pathway." (PMID 32210474, 2020). "The ability of SIGIRR to interact with various components of TLR signaling pathways in a manner that influences the immune response of epithelial cells during bacterial infection indicates its potential importance as a negative regulator during chlamydial infection." (PMID 32210474, 2020).
Cirrhosis (1 paper, 2021). A chronic disorder of the liver in which liver tissue becomes scarred and is partially replaced by regenerative nodules and fibrotic tissue resulting in loss of liver function. "Patients with decompensated cirrhosis presented a more limited alteration in TLR signalling genes, including 6 of the 17 upregulated genes observed in compensated cirrhosis, SIGIRR, IRAK1, HSPA1A, TOLLIP and ELK1, as well as downregulation of IL-1B." (PMID 34774066, 2021).
colon carcinoma (1 paper, 2022). "We showed that SIGIRRΔE8 expression promotes the metabolic shift through upregulation of mTOR (suppressing full-length SIGIRR) and/or dysregulation of mitochondrial function (interacting with ATP5A1) to promote survival and proliferation of colon cancer cells." (PMID 35900274, 2022).
gastroenteritis (1 paper, 2014). An inflammatory disorder that affects the upper and lower gastrointestinal tract. "In contrast, vancomycin pretreatment of mice deficient in SIGIRR (Sigirr−/−), a negative regulator of MyD88-dependent signaling led to heavy and widespread C. jejuni colonization, accompanied by severe gastroenteritis involving strongly elevated transcription of Th1/Th17 cytokines." (PMID 25033044, 2014). "While our data showed that SIGIRR deficiency facilitated the ability of C. jejuni to adhere to and infect intestinal epithelial cells in vivo, resulting in overt gastroenteritis, it was unclear whether the resulting pathology depended on C. jejuni pathogenicity factors." (PMID 25033044, 2014).
glioma (1 paper, 2022). A benign or malignant brain and spinal cord tumor that arises from glial cells (astrocytes, oligodendrocytes, ependymal cells). "In contrast, SIGIRR was expressed at similar levels in almost all cancer types, besides glioma and head-and-neck tumors, in which its expression levels were decreased compared to the rest (Figure 1Β)." (PMID 36551790, 2022).
Hepatic steatosis (1 paper, 2022). Steatosis is a term used to denote lipid accumulation within hepatocytes. "Additionally, peripheral blood leukocyte ACSL4, CRLS1, CTP1A, SIGIRR, SSBP1, and ZNF622 genes containing DMPs might be used as serum biomarkers to stratify NAFLD patients into groups with simple hepatic steatosis and NASH." (PMID 35433752, 2022).
keratitis (1 paper, 2012). A corneal disease that is characterized by inflammation of the cornea. "In a model of keratitis induced by P. aeruginosa, TIR8/SIGIRR was involved in down-regulating Th1 immunity and associated IL-1RI and TLR4-activation, thus preventing tissue damage and promoting resistance to infection." (PMID 23112799, 2012).
kidney cancer (1 paper, 2022). Primary or metastatic malignant neoplasm involving the kidney. "When we analyzed in silico data of different kidney cancer histotypes, we identified the clear cell subtype as the one where SIGIRR was mostly downregulated; nonetheless, papillary and chromophobe tumor types also showed low levels as compared to their normal counterpart." (PMID 35814450, 2022).
lupus-like syndrome (1 paper, 2012). "The current study was focused on SIGIRR as its deficiency has been shown to lead to the development of lupus-like syndrome in the mouse." (PMID 22952899, 2012).
pyelonephritis (1 paper, 2025). An inflammatory process affecting the kidney. "The findings revealed predominantly positive SIGIRR protein expression in cortical tubular epithelial cells, whereas SIGIRR mRNA levels were significantly decreased in the pyelonephritis model." (PMID 40583347, 2025).
renal carcinoma (1 paper, 2022). A carcinoma arising from the epithelium of the renal parenchyma or the renal pelvis. "Our study shows that SIGIRR downregulation in RCC cells unleashes an inflammatory signaling intrinsic to renal cancer cells that leads to NFKBIZ activation, IL6 induction, MMP1 upregulation, and notably higher levels of PD-L1 and ICAM1 expression." (PMID 35814450, 2022).
renal cell carcinoma (1 paper, 2022). "Overall, these results suggest that SIGIRR downregulation unleashes IL1 signaling intrinsic to renal cell carcinoma cells." (PMID 35814450, 2022).
respiratory infections (1 paper, 2014). "Thus, TIR-8/SIGIRR emerges as a non-redundant receptor for dampening inflammation and tissue damage in respiratory infections." (PMID 25375146, 2014).